KANK4 (KN motif and ankyrin repeat domains 4)
Description:
May be involved in the control of cytoskeleton formation by regulating actin polymerization.
Synonyms: ANKRD38; KIAA0172; dJ1078M7.1
Tractability: PROTAC: ubiquitination databases record sites on it.
Gene: Protein-coding gene on chromosome 1 (62,236,165 to 62,319,434, reverse strand). Ensembl gene ENSG00000132854.
Subcellular location: Cytoplasm
Subcellular location (Human Protein Atlas): Cytosol; Microtubules
Gene Ontology:
Molecular function: protein binding
Biological process: negative regulation of actin filament polymerization
Cellular component: cytoplasm; cytoskeleton
Genetic constraint (gnomAD): Loss-of-function variants: 47 observed, 72.3 expected, observed/expected ratio (o/e) 0.65, 90% interval 0.51 to 0.83. The upper end of that interval is the gene's LOEUF score, 0.83, which puts it in group 3 of 6, group 1 being the genes least tolerant of losing a copy. Missense variants: 1,143 observed, 1,224.1 expected, observed/expected ratio (o/e) 0.93, 90% interval 0.89 to 0.98. Synonymous variants: 427 observed, 492.14 expected, observed/expected ratio (o/e) 0.87, 90% interval 0.8 to 0.94.
Homologues: Orthologues: chimpanzee KANK4 (98% identical), macaque KANK4 (95% identical), dog KANK4 (82% identical), rabbit KANK4 (81% identical), mouse Kank4 (74% identical), rat Kank4 (74% identical), pig KANK4 (68% identical), guinea pig KANK4 (57% identical), zebrafish kank4 (32% identical), Drosophila melanogaster Kank (20% identical), Caenorhabditis elegans vab-19 (18% identical). Paralogues in human: KANK1 (31% identical), KANK2 (24% identical), KANK3 (22% identical).
Diseases named in the same sentence as KANK4 in open-access papers:
KANK4 is named in the same sentence as 6 diseases in open-access papers, as found by Europe PMC text mining. Sharing a sentence is not in itself a finding about the gene and the disease. The quoted sentences say what the papers report.
breast carcinoma (1 paper, 2025). "Only KTR14, KRT16, CXCL9, and CFD in BRCA1 Ovarian Cancer and TSPAN7 and CDKN2C in BRCA2 ovarian cancers were highly upregulated, and KANK4, MFGE8, LINC00346, and SA100A1 in BRCA1 mutated breast cancer, and MAGEA4 in BRCA2 breast cancers." (PMID 40647506, 2025). "In BRCA1-mut breast cancer, KANK4, MFGE8, LINC00346, and A100A1 were upregulated (more than 3-fold change), and in BRCA2-mut breast cancers, MAGEA4 was highly expressed (more than 4-fold change)." (PMID 40647506, 2025).
ependymoma (1 paper, 2024). A WHO grade II, slow growing tumor of children and young adults, usually located intraventricularly. "BST1, FLG, KANK4, and SHISA9 were significantly higher expressed in SP-EPN subtype A compared to all other ependymomas, whereas AK5, CFTR, RASSF6, and TBX22 showed high expression in subtype B." (PMID 38265489, 2024).
keloid (1 paper, 2024). An irregularly shaped, elevated mark on the skin caused by deposits of excessive amounts of collagen during wound healing. "The expression levels of TAGLN and KANK4 tend to be higher in keloid fibroblasts (n = 10) versus immature scar fibroblasts (n = 13) (P = 0.06 and 0.06, respectively)." (PMID 38622256, 2024). "Our results suggest that the KANK4-mediated increase in myofibroblast mobility contributes to keloid pathogenesis." (PMID 38622256, 2024). "Among significantly upregulated 112 genes, KN motif and ankyrin repeat domains 4 (KANK4) was identified as a specifically upregulated gene in keloids." (PMID 38622256, 2024). "Nevertheless, our study provides a new perspective on the pathogenesis of keloids, and highlights KANK4 as a potential target for keloid." (PMID 38622256, 2024). "KNAK4 expression was also upregulated by TGF-β in these fibroblasts; however, the increase in KANK4 expression was markedly more significant in keloid fibroblasts (P = 0.30 and 0.04 in FB2 and FB3, respectively) versus immature scar fibroblasts." (PMID 38622256, 2024). "To understand the function of KANK4 in keloid fibroblasts, we overexpressed KANK4 in the established immature fibroblasts (FB1) and keloid fibroblasts (FB2, FB3)." (PMID 38622256, 2024). "The result of qPCR using Primer set 2 revealed that KANK4 expression was significantly higher in keloid tissue versus immature scar tissue." (PMID 38622256, 2024). "We established fibroblasts from immature scar and keloid tissues to investigate the function of KANK4 in these cells." (PMID 38622256, 2024). "Immunohistochemical analysis showed that KANK4 protein was mostly expressed in TAGLN-positive myofibroblasts in keloid tissues." (PMID 38622256, 2024). "The results suggested the presence of distinct characteristics between myofibroblasts in keloids and those in immature scars, with KANK4 emerging as a specifically upregulated gene in keloids." (PMID 38622256, 2024). "Indeed, most myofibroblasts in keloids showed KANK4 expression; however, only a few myofibroblast in immature scars expressed KANK4." (PMID 38622256, 2024). "Although, we were unable to identify the mechanism regulating KANK4 expression in keloid myofibroblasts, we hypothesized that TGF-β might be involved in this process." (PMID 38622256, 2024). "In keloid tissue, KANK4-positive myofibroblasts may exhibit enhanced mobility and be able to migrate beyond the original wound and expand the keloid lesion by producing ECM." (PMID 38622256, 2024). "Furthermore, through further analysis showed that overexpression of KANK4 enhance cell mobility in keloid myofibroblasts." (PMID 38622256, 2024). "Overexpression of KANK4 enhanced cell mobility in keloid myofibroblasts." (PMID 38622256, 2024). "Next, we focused on KANK4 (i.e., one of the upregulated genes in keloids)." (PMID 38622256, 2024). "Further functional studies are needed to determine the precise role of KANK4 in keloid formation." (PMID 38622256, 2024). "Interestingly, the ratio of Primer set 2 to Primer set 1 was higher in keloid samples compared with immature scar samples, suggesting that the shorter isoform of KANK4 is expressed more abundantly in keloid tissue." (PMID 38622256, 2024). "Of those, six genes (i.e., OPCML, S100A7, S100 calcium binding protein A8 [S100A8], KANK4, PTPRD, tenascin XB [TNXB]) were significantly differentially expressed between keloid and immature scar samples." (PMID 38622256, 2024). "KANK4 was also induced by TGF-β in normal fibroblasts, immature scar fibroblasts and keloid fibroblasts, but the induction was much prominent in keloid fibroblast." (PMID 38622256, 2024). "Immunohistochemical analysis confirmed the expression of KANK4 protein in myofibroblasts within keloid tissues, whereas it was absent in myofibroblasts in immature scar tissues." (PMID 38622256, 2024).
keloid (continued). "Immunohistochemical analysis showed that KANK4 protein was expressed in myofibroblasts in keloid tissues; however, it was not expressed in any myofibroblasts in immature scar tissues." (PMID 38622256, 2024). "A limitation of this study is that, due to the absence of validation studies using animal models, we could not determine whether KANK4 overexpression actually leads to the development of keloids in vivo." (PMID 38622256, 2024). "Interestingly, TAGLN-negative fibroblasts did not express KANK4 in keloid samples." (PMID 38622256, 2024).
KANK4 also shares sentences with these, for which no sentence is quoted: cervical cancer (1 paper); infection (1); ovarian carcinoma (1).